BRCA2 (BRCA2 DNA repair associated)
Diseases named in the same sentence as BRCA2 in open-access papers (continued):
Sharing a sentence is not in itself a finding about the gene and the disease.
cancer (continued). "ATR inhibition is lethal with numerous cancer-associated changes, including oncogenic stress (oncogenic RAS mutations, MYC and G1/S-specific cyclin-E1 (CCNE1) overexpression), deficiencies in DNA repair (TTP53, BRCA1/2, partner and localizer of BRCA2 (PALB2) and ATM loss) and other defects." (PMID 32316968, 2020). "However, some women belonging to families with an identified pathogenic variant in BRCA1 or BRCA2 will develop cancer despite testing negative for the family’s pathogenic variants and are often denoted as phenocopies." (PMID 33198123, 2020). "Importantly, the cancer spectrum caused by mutations in PALB2 is quite similar to that induced by mutations in BRCA2, thereby validating the direct interaction between PALB2 and BRCA2." (PMID 32300589, 2020). "Given that MEILB2 and BRME1 are also aberrantly expressed in human cancer cell lines, the amplification of gene products involved in BRCA2 function and subsequent hijacking of the intrinsic HR pathway might be a driving force in the development of certain sporadic cancers." (PMID 32345962, 2020). "This implies that BRCA2 mutated (or BRCAness) cancers could not be suitable for anti-telomerase therapies, since they can intrinsically possess ALT activity that rescue proliferative potential of cancer cells." (PMID 31510074, 2019). "Hormone receptor-positive BC (regardless of the BRCA1/BRCA2 mutation status) is currently considered a cancer with a favorable prognosis, allowing the omission of adjuvant chemotherapy, shorter course of adjuvant hormonal treatment (no longer than five years), and other “de-escalation” approaches." (PMID 31141992, 2019). "Regarding the expression of the evaluated cytokeratins, the cancers associated with a germline pathogenic variant in BRCA1 were more frequently positive for CK5/6 and CK14 than tumors associated with a germline pathogenic variant in BRCA2 (p = 0.031 and p = 0.008, respectively)." (PMID 31244284, 2019). "Furthermore, some studies indicate that the cancer risk of BRCA1 and BRCA2 mutation carriers might be reduced by a healthy lifestyle (e.g. no smoking, physical activity)." (PMID 31370837, 2019). "Also, women with BRCA1- or BRCA2-associated cancer had an increased frequency of breast stem cells in noncancerous breast tissue, which were identified by expression of the stem and progenitor cell marker ALDH." (PMID 30930946, 2019). "Interestingly, the strongly reported predisposition gene BRCA2 is mostly indistinguishable for all six cancer types and is thus relatively insensitive to the described batch effect." (PMID 31391007, 2019). "However, the benefits might be limited to certain populations, such as patients with a mutation of breast cancer gene 1 (BRCA1), breast cancer gene 2 (BRCA2), or both (BRCA1/2)." (PMID 31795359, 2019). "Effects on gene expression caused by BRCA2 mutations could conceivably contribute to cancer etiology even in the absence of DNA damage." (PMID 29447171, 2018). "Thus, a therapeutic regimen that includes inhibitors for the DNA repair pathway, a tumor-specific platinum drug, together with radiotherapy may prove to be an effective way of treating and managing the cancer burden due to BRCA1 and BRCA2 mutations." (PMID 29459887, 2018). "These two variants, BRCA1:c.‐192T>C and BRCA2:c.‐296C>T, were observed in population subgroup controls; notably BRCA1:c.‐192T>C was observed at a frequency of >1%, which is considered stand‐alone evidence against pathogenicity (defined as high risk of cancer) for BRCA1/2 variation." (PMID 30204945, 2018). "Despite the rapid growth of next‐generation sequencing allowing for simultaneous testing of multiple genes linked to cancer risk, the clinical impact of pathogenic variants in genes beyond BRCA1 and BRCA2, especially in terms of CBC risk, is still largely unknown." (PMID 29733510, 2018).
cancer (continued). "In addition, multigene panel testing could identify up to 50% more individuals with cancer susceptibility gene mutations in comparison with testing only for BRCA1 and BRCA2 (BRCA)." (PMID 29566657, 2018). "These risks vary significantly according to (a) age at disease diagnosis in carriers of identical mutations, (b) the cancer site in the individual who led to the family’s ascertainment, (c) the degree of family history of the disease, and (d) the type and location of BRCA1 and BRCA2 mutations." (PMID 27796716, 2017). "Certain SNPs in DNA glycosylase genes could affect negatively to the general performance of the BER pathway and contribute by increasing the levels of genome instability and hence to a higher cancer risk, especially in presence of a defective BRCA1 or BRCA2 background." (PMID 29383107, 2017). "Furthermore, factors required for replication fork stability, repair and restart in response to RS, such as the BRCA1 and BRCA2 proteins, SLX4, and FA group members, have all been shown to associated with cancer development when their function is compromised in either human or mouse models." (PMID 28445142, 2017). "It is known that PALB2 cancer-related missense variants L393W, T1030I and L1143P in the WD40 domain could interfere with PALB2 association with RAD51 and BRCA2, prompting carriers to be defective in DNA damage repair by HR, leading to an increased sensitivity to IR-treatment." (PMID 28858227, 2017). "We searched relevant articles from PubMed, Embase, Web of Science, and the Cochrane Library databases to evaluate the differences in the overall survival (OS) and cancer-specific survival (CSS) between BRCA2 mutation carriers and non-carriers in patients with PCa." (PMID 28410213, 2017). "Furthermore, patients with BRCA1 mutation cancers had worse TTP and OS compared to those with BRCA2 mutation cancers, and our data suggest that this could potentially be related to an increased incidence of RDR." (PMID 29262651, 2017). "Our observations suggest that mutations in BRCA2 but not BRCA1 genes are linked with the initiation of the oncogenic process rather than with a clear role in the progression of the tumor or sensitivity to anti-cancer treatment." (PMID 27149669, 2016). "Therefore, how to counsel women with family history of OvC but without BRCA1 or BRCA2 mutations has remained a major unresolved question in clinical cancer genetics." (PMID 26025000, 2015). "As mutations in BRCA1 and BRCA2 may predict response to PARP inhibition regardless of cancer type, clinical trials testing the efficacy of PARP inhibitors in cancer with BRCA1 or BRCA2 mutations may need to be extended to all disease types, including HCC." (PMID 26449224, 2015). "Thus, developing therapeutic strategies targeting RAD52 to treat PALB2, BRCA1 or BRCA2 mutant cancers might be considered." (PMID 26610585, 2015). "Thus no new deleterious mutations were identified in cancer cases representative of 37 French Canadian HBC/HBOC families found negative for deleterious BRCA1/ BRCA2 mutations." (PMID 25925845, 2015). "In a recent statement of the International Cancer of the Pancreas Screening (CAPS) Consortium, most members felt that BRCA2 mutation carriers with ≥ 1 affected first-degree relative, or with two affected relatives (whether or not first degree), should be considered candidates for screening." (PMID 26844277, 2015).
cancer (continued). "Moreover, one case (Patient P) had a germline frameshift mutation in exon 13 of BRCA2 mutation along with somatic loss of the non-mutated allele in the cancer." (PMID 25916844, 2015). "In addition, Patient G has a germline BRCA2 P451Q VUS that became homozygous in the carcinoma." (PMID 25916844, 2015). "Until recently, a significant issue surrounding multigene panel testing for cancer susceptibility was that BRCA1/BRCA2 could not be included due to patents held by Myriad Genetics." (PMID 24763289, 2014). "However, PARP1 inhibition and the subsequent synthetic lethality can be used on other cancers that do not have mutations in BRCA1 or BRCA2 but that have a defect in the HR pathway, including mutations in ATM, Chk2, Rad51, and NBS1." (PMID 24795863, 2014). "The Consortium of Investigators of Modifiers of BRCA1 and BRCA2 (CIMBA), was established in 2006 and with more than 40,000 mutation carriers currently provides the largest sample size for reliable evaluation of even modest associations between single-nucleotide polymorphisms (SNPs) and cancer risk." (PMID 24698998, 2014). "Failure to cleave RAD21 due to BRCA1-dependent caspase 3 inhibition may explain loss of HR repair in BRCA1 but not in BRCA2 cancers." (PMID 22537934, 2012). "However, its expression associates with a poor prognosis in BRCA2 and BRCAX cancers." (PMID 22537934, 2012). "Consistently, cancer-associated genes that had not been previously associated to AP-2 were identified in the tumor extracts datasets, as for instance the breast cancer susceptibility gene 2 (BRCA2) and the cyclin-dependent kinase 2 gene." (PMID 21876733, 2011). "Women with the same BRCA2 mutation may develop breast, ovarian or other cancers at different ages or not at all." (PMID 21060860, 2010). "Thus, GEN1 might join the number of genes involved in recombinational repair such as BRCA1, BRCA2, and FANCJ/BACH, mutation of which is associated with cancer." (PMID 20661466, 2010). "In addition, eight of 125 known cancer susceptibility alleles identified by previous GWAS of other cancers were associated with BRCA2 modification in the current study, a number not greater than expected (Kolmogorv-Smirnov p = 0.60) by chance alone." (PMID 21060860, 2010). "While reduction in cancer-specific mortality is the gold standard for surveillance tools, there is a pressing need to supplement mammography in high-risk women, particularly for BRCA1 and BRCA2 mutation carriers who are diagnosed with a high rate of interval tumors, roughly 50%." (PMID 16800895, 2006). "Many persons with a germline inactivating mutation of BRCA2 do not get cancer." (PMID 16417627, 2006). "In self-identified White patients, PGV rates in ATM, BRCA1, BRCA2, CHEK2 and Lynch genes were significantly higher compared to two cancer-free male cohorts." (PMID 40832411, 2025). "However, the opposite also seems possible, namely that, in cases of BRCA2-associated cancers with acquired chemotherapy resistance, PVs that do not allow for a rescue mechanism may confer drug insensitivity despite variant splicing." (PMID 40724944, 2025). "In a large pan-cancer BRCA1/2 analysis, biallelic inactivation occurred in only 50% of BRCA1 mutants versus 90% of BRCA2 mutants." (PMID 39333696, 2025).
cancer (continued). "In such a scenario, it would be predicted that BRCA-proficient cancer cells need to enhance the activation of homologous recombination factors such as BRCA1, BRCA2, and RAD51 to repair dsDNA breaks." (PMID 40243501, 2025). "To examine whether UCP1-CRISPRa mammary adipocytes might prevent cancer development in individuals at high lifetime risk of cancer, we co-cultured them alongside breast organoids from dissected patient-matched breast tissue of BRCA1/BRCA2/RAD51D mutation carriers." (PMID 39905264, 2025). "Nine (9/89; 10.1%) of the BRCA1/BRCA2 MINAS cases within this review were reported by Leegte, van der Hout who reported a younger median age of cancer onset in BRCA1/BRCA2 MINAS at 40.8 years vs. 48 years for single BRCA1/BRCA2 carriers." (PMID 39843919, 2025). "Mutation-specific cluster regions (CR) in both genes have been identified for breast (BCCR) and ovarian (OCCR) cancer, aiding in the monitoring of patients with PVs in BRCA1 and BRCA2." (PMID 40071159, 2025). "Among cancer cases performed using MLPA, six cases of BRCA1 showed CNV values matching ddPCR results (CNVs = 1.6 ± 0.1), while eight cases of BRCA2 detection matched with ddPCR results (CNVs = 1.9 ± 0.1)." (PMID 40725150, 2025). "For cell cycle regulation and cancer, the genes CCND1 and E2F7 (cell cycle regulation) and BRCA2, NF2, BRCA1, and NF1 (cancer) were found to be upregulated relative to humans." (PMID 40149424, 2025). "A younger median of cancer was similarly reported in Koreans by Bang, Kwon (33.7 years) and Hur, Kim (36 years) when compared to single BRCA1/BRCA2 carriers." (PMID 39843919, 2025). "CTCF depletion leads to the disruption of chromatin organization around the DNA damage sites, which abolishes the recruitment of essential DNA damage repair proteins BRCA2 and RAD51, as well as impairs homologous repair in the IDH mutant cancer cells." (PMID 39920158, 2025). "Biomarkers in BC often focus on obvious genes in line with hallmarks of cancer that contribute to malignant tumor growth, particularly oncogenes and tumor suppressor genes (i.e. BRCA1 and BRCA2)." (PMID 39838298, 2025). "BRCA1 PV carriers were significantly younger at cancer onset and presented with more aggressive tumor subtypes, such as TNBC and higher Ki-67 values, than BRCA2 PV or WT carriers." (PMID 40422528, 2025). "BRCA2 and Lynch genes PGV rates were significantly higher in PCa patients compared to a cancer-free control cohort in SIRE-Black men." (PMID 40832411, 2025). "To date, a significant number of studies have focused on classifying VUS identified in the BRCA2-DBD, largely due to its functional importance and cancer relevance." (PMID 40232841, 2025). "Delaying surgery by 5 years for BRCA1 (RRM at age 35 years; RRSO at age 40 years) and BRCA2 (RRM at age 40 years; RRSO at age 45 years) was still cost-effective but with reduced QALYs and NMB and fewer cancers prevented." (PMID 38334999, 2024). "Wnt signaling was likewise differentially regulated when 4T1 BRCA2-null and 4T1 BRCA1-null cancer cells were compared (P = 0.013)." (PMID 39028933, 2024). "A further scenario for BRCA2 PV carriers (RRM at age 30 years; RRSO at age 35 years) yielded more QALYs and a greater NMB with more cancers prevented." (PMID 38334999, 2024). "In vitro study suggested that 6-G possesses anti-cancer activity by inducing cell apoptosis in human PCa PC-3 cells by affecting AR regulated DDR genes (BRCA1, BRCA2, and ATM ) which is involved in cell survival." (PMID 38166796, 2024).
cancer (continued). "Gene-level analysis of variant prevalence revealed no significant enrichment of PLP variants in specific genes when comparing the healthy individuals (4 for BRCA1, 6 for BRCA2) and cancer patients (8 for BRCA1, 12 for BRCA2) (Fisher’s Exact P = 0.745)." (PMID 38566028, 2024). "We subsequently sought to identify the most promising synthetic viability candidates by integrating cancer genomic and transcriptomic analyses with results from recent genome-wide CRISPR knockout screens in BRCA1 and BRCA2 knockout isogenic cell lines." (PMID 39198848, 2024). "In contrast to the aggregation of PLP variants within the functional domains of BRCA (BRCA2 BRC repeat and DNA-binding) in cancer patients, we observed a uniformed distribution of PLPs across BRCA1 and BRCA2 sequence in the healthy individuals." (PMID 38566028, 2024). "To evaluate the effect of these conditions on cancer cell growth, we conducted CCK8 assays in TYK‐nu cells with stable BRCA1/BRCA2 knockdown." (PMID 39690136, 2024). "Resultantly, NHS England Cancer Programme introduced clinical implementation of population-based BRCA1 and BRCA2 testing for all UK Jewish adults in January 2024." (PMID 39001386, 2024). "Therefore, we investigated the evolutionary history of cancer associated gene sequences across 384 mammalian taxa, to detect signatures of selection across categories of oncogenes (GRB2, FGL2 and CDC42), tumour suppressors (LITAF, Casp8 and BRCA2) and immune genes (IL2, CD274 and B2M)." (PMID 38773187, 2024). "However, this might not be the case for hereditary cases, with BRCA2-related cancer as a prominent example where tumours most often are ER-positive but BRCA1/BRCA2-deficient." (PMID 37316882, 2023). "Collectively, our work reveals two distinct mechanisms of BRCA2-dependent RAD51 loading onto ssDNA, which we propose are critical for its diverse functions in maintaining genome stability and cancer suppression." (PMID 37499663, 2023). "After excluding patients who underwent chemotherapy or surgery before the ultrasound, we evaluated 89 cancers in BRCA1-positive and 83 in BRCA2-positive patients." (PMID 36905492, 2023). "Our study aims to present the prevalence and geographic distribution of an inherited BRCA2 PV identified in HBOC families, followed by our Cancer Genetic Counselling Service and coming from a specific limited area of the eastern coast of Emilia Romagna." (PMID 37046793, 2023). "Lastly, in a pan-cancer analysis of germline and somatic BRCA alterations of several cancers, uterine LMS harbored the highest rate of somatic homozygous BRCA2 deletion." (PMID 36969049, 2023). "In contrast, the tumour with bi-allelic BRCA2 inactivation and RAD51D c.202G > A (tumour 46) was classified as BRCA2-like supporting the inactivation of BRCA2 as the driver of this cancer." (PMID 37316882, 2023). "The “Use with Caution” antibodies in this set include antibodies that bind the protein products of frequently altered cancer driver genes, such as the oncogenes MYC and BRAF and the tumour suppressors BRCA2 and VHL." (PMID 37169592, 2023). "Of these, the most commonly seen are in the Breast Cancer gene 1 (BRCA1), Breast Cancer gene 2 (BRCA2), Checkpoint kinase 2 (CHEK2) and partner and localizer of the BRCA2 gene (PALB2) tumour suppressor genes." (PMID 36831687, 2023). "In major studies, 18 target genes such as BRCA1,BRCA2, and PALB2 were reported as biomarkers for cancer progression and development." (PMID 39430039, 2023). "BRCA is a cancer suppressor gene, including BRCA1 and BRCA2, identified in 1990 and 1994, respectively." (PMID 37476378, 2023).